CARD17P (caspase recruitment domain family member 17, pseudogene)
Description:
Regulator of procaspase-1/CASP1 activation implicated in the regulation of the proteolytic maturation of pro-IL-1beta/IL1B and its release during inflammation. Inhibits the release of IL1B in response to LPS in monocytes. However, unlike CASP1, do not induce NF-kappa-B activation.
Synonyms: INCA; formerly CARD17
Gene: Transcribed unprocessed pseudogene on chromosome 11 (105,092,486 to 105,101,414, reverse strand). Ensembl gene ENSG00000255221.
Subcellular location: Cytoplasm
Diseases named in the same sentence as CARD17P in open-access papers:
CARD17P is named in the same sentence as 3 diseases in open-access papers, as found by Europe PMC text mining. Sharing a sentence is not in itself a finding about the gene and the disease.
CARD17P shares sentences with these, for which no sentence is quoted: pulmonary TB (1 paper); respiratory diseases (1); sarcoidosis (1).